AXIN1 (axin 1)
Diseases named in the same sentence as AXIN1 in open-access papers (continued):
Sharing a sentence is not in itself a finding about the gene and the disease.
tumor (132 papers, 2004 to 2026). "AXIN1 mutations can lead to abnormal expression of immune checkpoint molecules (such as PD-L1) on the surface of tumor cells." (PMID 39897920, 2025). "Wnt–β-catenin pathway dysregulation is often caused by mutations in various pathway components, particularly mutations or silencing of Wnt tumor suppressor genes, Axin1/2 mutations, and GSK3β loss." (PMID 40818609, 2025). "Although we found that the impact of metformin on tumor metabolism were dependent on AXIN1, the underlying mechanisms of how AXIN1 mediates this process is unclear." (PMID 39308524, 2024). "The AXIN1 rs1805105 G/A polymorphism was associated with almost three folds of larger tumor size (≥1 cm)." (PMID 36510340, 2023). "AXIN1 acts as a tumor suppressor, and mutations in this protein have been shown to play a significant role in carcinogenesis." (PMID 31143301, 2019). "It is also enriched (28% samples) for mutations in AXIN1, a tumor suppressor gene that regulates the Wnt signaling pathway." (PMID 30367051, 2018). "The underlying mechanism of 5-HT1DR-promoted tumor invasion was through its activation on the Axin1/β-catenin/MMP-7 pathway." (PMID 26214021, 2015). "Both CTNNB1 (58% vs. 16%) and AXIN1 (54% vs. 16%) mutations were significantly enriched in patients undergoing a subsequent recurrence of their tumor (P = 0.0045 and P = 0.0022, respectively)." (PMID 25502816, 2014). "Insight in how phosphorylated β-catenin is removed from the Axin1 complex and delivered to the ubiquitin–proteasome system will be required to fully understand how cancer mutations derail Wnt signalling to drive tumour growth." (PMID 25392450, 2014). "In addition, we found that truncating mutations near the canonical start site of AXIN1 result in alternative translation initiation and, consequently, expression of an N-terminally truncated variant with residual tumor suppressor function." (PMID 41550750, 2026). "The AXIN1 rs1805105 polymorphism was associated with larger tumor size (≥1 cm)." (PMID 36510340, 2023). "AXIN1 rs1805105 G/A polymorphism was associated with higher tumor size." (PMID 36510340, 2023). "Studies have shown that the AXIN1 rs1805105 polymorphism is correlated with the early tumor stages (I and II, modified by the Union for International Cancer Control) and the small tumor size (under 5 cm) of HCC but increases the risk of developing advance-stage renal carcinogenesis (RCC III and IV)." (PMID 31143301, 2019). "In animal models, it was reported that overexpression of the 5-HT1D receptor was associated with the Wnt signaling pathway and an advanced tumor stage, and its antagonist could effectively inhibit tumor metastasis through suppressing Axin1, a Wnt-signaling downstream gene." (PMID 40710186, 2025). "Axin1 is known to function as a tumor suppressor by scaffolding the β-catenin destruction complex to promote β-catenin degradation; therefore, sgAxin1 is expected to stabilize β-catenin and activate β-catenin signaling." (PMID 41512056, 2026). "Recent genome sequencing efforts of HCC patient cohorts revealed that mutations in AXIN1 and CTNNB1 are mutually exclusive and associate with distinct tumor characteristics, aggressiveness, and clinical prognosis." (PMID 41550750, 2026). "Nearly half of HCCs are Wnt-active with mutations in CTNNB1 (encoding for β-catenin), AXIN1/2, or APC, and demonstrate heterogeneous and limited benefit to ICI due to an immune excluded tumor microenvironment." (PMID 40442146, 2025). "Mutations in APC, AXIN1, and CUX1 are known to promote tumor aggressiveness, stemness, and metastatic dissemination." (PMID 40842629, 2025).
tumor (continued). "PLA foci indicating Ephexin1 and Axin1 interactions were markedly greater in cancer tissues than in normal tissues and significantly increased with tumor grade and metastasis." (PMID 39741188, 2025). "A defining strength of AI-HOPE-WNT lies in its ability to dynamically stratify CRC patient cohorts by WNT gene mutation status (e.g., APC, AXIN1/2, RNF43), tumor location, age group, treatment exposure (e.g., FOLFOX), and molecular phenotype (e.g., MSI)." (PMID 40860720, 2025). "Using natural language queries, AI-HOPE-WNT investigated co-mutation patterns between AXIN1 and APC by tumor location." (PMID 40860720, 2025). "Mutations in tumor suppressors, such as APC, Axin1/2, and RNF43, as well as β-catenin mutations, are common in many cancers." (PMID 40943055, 2025). "In GC tissues, TRIM11 expression inversely correlates with Axin1 protein levels, underscoring its role in destabilizing Axin1 and activating Wnt/β-catenin signaling to drive tumor progression." (PMID 40936722, 2025). "Since AXIN1 is a negative regulator of WNT/β-catenin signaling, its mutation can lead to aberrant pathway activation, contributing to tumor growth and metastasis." (PMID 40282485, 2025). "What's more, treatment SR3029 suppressed tumor growth by stabilizing AXIN1 in xenograft tumor model." (PMID 38419282, 2024). "Future studies are required to further investigate the role of these metabolites and the mechanism by which AXIN1 affects metformin’s regulation of tumor metabolism." (PMID 39308524, 2024). "Conversely, deubiquitination modifications of AXIN1 often lead to protein stabilization, underscoring its tumor-suppressive role." (PMID 38291457, 2024). "In vivo, a subcutaneous xenograft model using BALB/c nude mice confirmed that TRIM31 facilitated Axin1 degradation to promote tumor growth and progression." (PMID 39768197, 2024). "Nearly half of HCCs are Wnt-active with mutations in CTNNB1 (encoding for β-catenin), AXIN1/2, or APC, and demonstrate limited benefit to ICI due to an immune excluded tumor microenvironment." (PMID 39711542, 2024). "The AXIN1 tumour suppressor is an inhibitor of the Wnt signalling pathway, which plays critical roles in embryonic development and adult tissue homeostasis." (PMID 38396644, 2024). "Currently, various miRNAs have been identified as regulators that inhibit AXIN1 post-transcriptionally, thereby promoting tumor progression." (PMID 38291457, 2024). "Molecularly, all tumor models exhibit common driver mutations in CTNNB1 and AXIN1, with TLCT models showing the characteristic TERT mutation, and some models progression-associated alterations in the NFE2L2 and NRAS genes." (PMID 39529166, 2024). "In summary, the current study demonstrated that metformin promotes anti-tumor immunity in STK11 mutant NSCLC in an AXIN1-dependent manner through the upregulation of multiple nucleotide metabolites." (PMID 39308524, 2024). "Depending on AXIN1 expression in H460 cells, metformin upregulated multiple nucleotide metabolites through metabolic pathways and promoted anti-tumor immunity in STK11 mutant NSCLC." (PMID 39308524, 2024). "Axin1 protein expression was decreased remarkably in tumor specimens when compared to normal tissues." (PMID 38715121, 2024). "YTHDF2, by binding to and stabilizing AXIN1 expression, enhances tumor cell resistance to chemotherapy in cervical cancer cells." (PMID 38291457, 2024). "AXIN1 is a tumor suppressor and a crucial negative regulator of the Wnt/β‐catenin signaling pathway." (PMID 38419282, 2024).
tumor (continued). "A recent study reported that Axin1 stimulates intestinal inflammation via an interferon-gamma/Th1 program that prevents tumor growth." (PMID 38010886, 2023). "A number of potential collaborative tumor suppressor genes were identified in the in vivo screen, with Axin1 and Prkar1a selected for further investigation." (PMID 35000262, 2022). "Active GSK3β binds to CK1 (Casein Kinase 1), APC (Adenomatous Polyposis Coli), AXIN1 and other members of the destruction complex to inhibit tumor development by phosphorylation and subsequent degradation of the oncogenic β-catenin protein." (PMID 35814427, 2022). "For further analysis, we selected two candidate genes, Axin1 and Prkar1a, in addition to the canonical tumor suppressor Pten." (PMID 35000262, 2022). "Although Axin1 has been widely regarded as a tumor suppressor, Axin2 plays a key regulatory function in the Snail-mediated EMT program and cancer progression caused by the nuclear-cytosolic shuttling of GSK-3." (PMID 34298652, 2021). "Intriguingly, T1 and T3 of HCC10 showed distinct branches for these two tumor regions possessed different mutational loci in TSC2, even though they shared a common ancestor in mutations including AXIN1, STK11 and TERT." (PMID 34211467, 2021). "Altogether, 6 genetic alterations of AXIN1 were detected in our PTC and tumor-free samples, however, the mutational patterns were markedly different." (PMID 31758407, 2020). "A nonsense mutation in AXIN1 has been found in one case of EC tumor, while a frameshift mutation in AXIN2 resulting in truncation has been found in another EC tumor." (PMID 31829231, 2019). "Consistent with the suppression of β-catenin and Wnt3A, we conclude that anti-proliferative effects of itraconazole on tumor cells are facilitated by modulating Wnt3A and β-catenin, and negatively regulate gene Axin-1." (PMID 28212537, 2017). "Accordingly, RNA-seq and immunohistochemical analyses demonstrate an ER-dependent correlation between RUNX1 and AXIN1 in tumour biopsies." (PMID 26916619, 2016). "Given the evidence from cell culture and animal models for combinatorial regulation of AXIN1 by RUNX1 and oestrogens, the analyses of the RNA-seq and the TMA data suggest ER-dependent regulation of AXIN1 by RUNX1 in patient tumours as well." (PMID 26916619, 2016). "Our in vitro data further showed that GR127935 functions as a tumor suppressor via Axin1/β-catenin/MMP-7 pathway in the cell cycle, proliferation, and invasion." (PMID 26214021, 2015). "To investigate the potential mechanism of Caco-2 cells and LoVo cells, we used PCR to examine the expression of mRNA in 19 genes including their difference in the tumor sample previously found and Axin1, LEF1, TCF4." (PMID 26214021, 2015). "When we treated these tumor-bearing mice with sumatriptan, the fluorescence activity of Axin1 decreased in a dose-dependent manner." (PMID 26214021, 2015). "Axin1 over-expression exerted its known tumor suppressor function, showing a profound effect on HT-1080 as well as on U2OS anchorage-independent growth ability, phenocopying the pharmacological effects of SEN461 at the phenotypic level." (PMID 24842792, 2014). "At the molecular level, SEN461 treatment enhanced the stability of the scaffold protein Axin1, a key negative regulator of the Wnt signaling with tumor suppressor function, resulting in downstream effects coherent with inhibition of canonical Wnt signaling." (PMID 24842792, 2014). "In several tumour types, TCF/β-catenin activation is caused by mutations in either adenomatous polyposis coli (APC), β-catenin exon 3, AXIN1, AXIN2 or β-transducin repeat-containing protein (β-TrCP)." (PMID 14970870, 2004). "Activated Wnt signalling in tumours is caused by increased levels of β-catenin, which can be the result of mutations in APC, β-catenin, AXIN1, AXIN2 or β-TrCP." (PMID 14970870, 2004).
tumor (continued). "SSCP analysis of the AXIN1 gene in 17 tumour/normal DNA pairs from tumours with strong nuclear β-catenin expression revealed six different aberration patterns." (PMID 14970870, 2004). "To gather more information about this possibility, we investigated AXIN1 gene LOH with the detected SNPs in a series of 20 tumours from our previous study with strong, normal membranous β-catenin expression." (PMID 14970870, 2004). "This is in accordance with studies that demonstrated biallelic inactivation of the AXIN1 gene in several tumour types, although heterozygous AXIN1 gene inactivation has also been described." (PMID 14970870, 2004). "The degradation of Axin1 further activates glycolysis-related signaling pathways, thereby enhancing the glycolytic capacity of EC cells and promoting the survival and invasion of tumor cells at the metabolic level." (PMID 41458606, 2025). "Additionally, AXIN1 polymorphisms were detected in 10.9% of HCC patients, further supporting the role of AXIN1 genetic alterations in tumor progression." (PMID 40344393, 2025). "Furthermore, ITZ was found to downregulate tumor markers such as Ki-67 and key components of the Wnt/β-catenin signaling pathway, including Wnt-3a and β-catenin, while upregulating Axin-1 expression." (PMID 40697374, 2025). "In HCC, PLX-4720 bound to AXIN1 to block tumor proliferation in TRAF2−/− mice on a high-fat diet." (PMID 40901678, 2025). "Moreover, as an oncogene, TRIM65 promoted cell growth and tumor metastasis in HCC via ubiquitylation of Axin1 to activate the β-catenin signaling pathway." (PMID 40438593, 2025). "The tankyrase inhibitor XAV939 could reduce the expression of β‐catenin by upregulating AXIN1, increase apoptosis induced by 5‐Fu and suppress tumor growth in CRC." (PMID 38419282, 2024). "Point mutations of CTNNB1 and AXIN1, likely activating the WNT pathway, also were restricted to invasive or metastatic stages often contributing to genetically heterogeneous subclones within the primary tumor." (PMID 39034322, 2024). "Nevertheless, in this case, the FOXE1 germline variant and co-occurring AXIN1 inactivation did not appear to be sufficient for tumour initiation." (PMID 38396644, 2024). "Germline FOXE1 and AXIN1 variants might have a role in thyroid ectopy and cleft palate, which, together with MAPK pathway activation, may contribute to tumours’ malignant transformation." (PMID 38396644, 2024). "Axin1 is a scaffold protein which plays a tumor suppressor role." (PMID 36510340, 2023). "However, the expression analysis showed that AXIN1 was highly expressed in ESCA tumor tissues compared to adjacent normal tissues, contradicting the prognosis results." (PMID 36475339, 2023). "Axis inhibition protein 1 (Axin1) is a scaffold protein that exerts its role as a tumor suppressor." (PMID 36510340, 2023). "RUNX1 has been shown to facilitate AXIN1 mediated suppression of β-catenin by inhibiting estrogen-dependent signaling, specifically in ER+ disease, where low expression of AXIN1 was associated with low RUNX1 expression, unveiling a potential mechanism for RUNX1-mediated tumor suppression." (PMID 36831308, 2023). "Of the members of this signaling pathway, the APC, AXIN1, TCF7L2, and RHOA genes are most frequently mutated, the latter encoding a low-molecular-mass protein that contributes to cell invasiveness, adhesion, migration, and polarization, and tumor metastasis." (PMID 37509254, 2023).
tumor (continued). "Of note, they found 6 mutations in AXIN1 in the 87 tumor samples that had no CTNNB1 mutations, underlining the significance of AXIN1 mutation in human HCC." (PMID 35453784, 2022). "It was demonstrated that HBV-related HCCs present a lower expression of AXIN1 in relation adjacent non-tumor tissues, suggesting that low expression levels of AXIN1 might contribute to the oncogenic potential of the gtF1b Basal cluster." (PMID 35966715, 2022). "Mice with truncation mutations in APC which preserve the SAMP regions do not develop tumors, whereas truncations removing the SAMP sites cause adenomatous polyposis, highlighting the importance of the binding of APC to Axin 1 and 2 for tumor suppression via destruction of β-catenin." (PMID 32823838, 2020). "The tumor suppressor function of AXIN1 and AXIN2 proteins in the Wnt signaling pathway has long been hypothesized, based largely on their roles in the β-catenin destruction complex." (PMID 31143301, 2019). "However, the role of AXIN1/2 as a tumor suppressor through the canonical WNT pathway remains controversial, as other findings have suggested that most human Axin1 mutated HCCs do not show a β-catenin activation program." (PMID 31382613, 2019). "Axin1 is a key component favoring the DC activity and many upstream molecules of Wnt/β-catenin pathway could meditate its activation by targeting Axin1 in tumor cells." (PMID 31649207, 2019). "However, immunohistochemistry analyses of Axin1 displayed a downregulation in the tumor of mice treated with GR127935 compared with that of the control group." (PMID 26214021, 2015). "However, the tumor/normal log2 ratios of AXIN1, CREBBP, GSK3A, and NKD2 in the BRAF wildtype samples were low (−0.26 median, 0.12 standard deviation) compared with those in the BRAF mutated samples (−0.02 median, 0.12 standard deviation)." (PMID 23324568, 2013). "In addition, AXIN1 protein expression was investigated by immunohistochemistry in all 37 tumour samples." (PMID 14970870, 2004). "No consistent differences in AXIN1 protein expression were observed between tumours with and without AXIN1 locus loss, irrespective of nuclear or membranous β-catenin expression." (PMID 14970870, 2004). "In addition, reduced protein expression of AXIN1 has recently been reported to correlate with tumour progression in oesophageal squamous cell carcinoma." (PMID 14970870, 2004). "To confirm whether these nucleotide metabolites that were upregulated in metformin-treated H460 cells but down-regulated in metformin-treated Axin1-/- H460 cells, were involved in metformin-induced anti-tumor immunity, we first examined the production of ADP upon metformin treatment." (PMID 39308524, 2024). "Furthermore, Ctnnb1 expression was increased in tumours compared to both FL and RD livers and among the components of the β-catenin destruction complex, Axin1 and the known β-catenin target Axin2 was significantly upregulated, while Apc, Gsk3a and Gsk3b were not differentially expressed." (PMID 37907668, 2023).